ANO7 (anoctamin 7)
Diseases named in the same sentence as ANO7 in open-access papers:
ANO7 is named in the same sentence as 19 diseases in open-access papers, as found by Europe PMC text mining. Sharing a sentence is not in itself a finding about the gene and the disease. The quoted sentences say what the papers report.
prostate carcinoma (22 papers, 2009 to 2025). A carcinoma that arises from epithelial cells of the prostate gland. "The transition of prostate cancer from localized to metastatic stages is further highlighted by the documented diminution and eventual loss of ANO7 expression." (PMID 39923095, 2025). "Our previous research has demonstrated a significant association between single-nucleotide polymorphisms (SNPs) in the ANO7 gene and the risk of aggressive prostate cancer." (PMID 39923095, 2025). "Genome-wide association studies (GWAS) and extensive meta-analyses have identified 451 distinct risk variants associated with prostate cancer, including four notable variants in the anoctamin 7 (ANO7) gene." (PMID 39923095, 2025). "ANO7 has been observed to be downregulated in metastatic disease, and decreased protein expression has been associated with high-grade prostate cancer." (PMID 39114022, 2024). "Anoctamin 7 (ANO7), an anion channel protein, has been implicated in prostate cancer and other types of cancer." (PMID 38224713, 2023). "The prostate cancer-associated gene ANO7 is downregulated in advanced prostate cancer, whereas benign tissue and low-grade cancer display varying expression levels." (PMID 36674564, 2023). "To investigate the impact of the A allele of rs77559646 on endogenous ANO7 mRNA splicing, we utilized an RNA-Seq data set consisting of matched benign and tumor samples from 49 prostate cancer patients." (PMID 35043958, 2022). "Our study is the first to provide a mechanistic explanation for the impact of a prostate cancer risk SNP on ANO7 protein production." (PMID 35043958, 2022). "ANO7 has been associated with prostate cancer in a large number of studies, and several risk SNPs in ANO7 have been identified." (PMID 35043958, 2022). "As elevated expression of ANO7 is associated with poor survival in prostate cancer patients, they aimed to identify interactors of ANO7." (PMID 34638309, 2021). "It should, however, be noted that although ANO7 upregulation is associated with good prognosis in breast and colon cancer, it is in fact associated with poor prognosis in prostate cancer." (PMID 32764426, 2020). "Anoctomin-7 (ANO7) is a member of the anoctamin family of Ca2+ activated Cl− channels, highly expressed by the prostate, and associated with aggressive prostate cancer." (PMID 33114768, 2020). "In addition to TERT, we found rare non-synonymous variants in three genes associated with decreased prostate cancer risk (ANO7, SPDL1 and AR), and three genes associated with increased risk (HOXB13, CHEK2 and BIK)." (PMID 39971927, 2025). "We suggest that loss of ANO7 contributes to prostate cancer progression." (PMID 35043958, 2022). "However, since a hereditary partial loss of ANO7 brings along an increased risk of aggressive prostate cancer, ANO7 is expected to exert some kind of anti-cancer function in the prostate." (PMID 35043958, 2022). "The nuclear enrichment of ANO7 mRNA was validated in prostate cancer cell lines 22Rv1 and MDA PCa 2b using droplet digital polymerase chain reaction (ddPCR) on RNA isolated from nuclear and cytoplasmic fractions of the cells." (PMID 36674564, 2023). "The enrichment of ANO7 transcripts in the nucleus was validated using ANO7-expressing prostate cancer cell lines MDA PCa 2b and 22Rv1." (PMID 36674564, 2023). "ANO7 has been shown to be downregulated in metastatic disease, and reduced protein expression is related to high-grade prostate cancer." (PMID 38224713, 2023). "Our results support the downregulation of both ANO7 mRNA and protein levels in high-grade prostate cancer, and ANO7 mRNA expression appeared restricted to luminal cells." (PMID 36674564, 2023). "These two cell lines both represent advanced prostate cancer, stages in which ANO7 tends to be downregulated." (PMID 35043958, 2022).
prostate carcinoma (continued). "Previous studies have shown that full-length ANO7 protein localizes apically and laterally in the benign prostatic epithelium, and that the expression is reduced in high grade prostate cancer compared to low grade cancer and normal prostate epithelium." (PMID 35043958, 2022). "ANO7 has been found to play a central role in prostate cancer progression, and its elevated expression correlates with disease severity and outcome." (PMID 34922623, 2021). "In conclusion, this study provides a compelling foundation for future investigations into the precise mechanisms through which ANO7 influences prostate cancer progression and the potential clinical applications of these findings in the diagnosis and treatment of prostate cancer." (PMID 39923095, 2025). "ANO7 has been suggested to be used as a diagnostic marker and a target for immunotherapy, but a full comprehension of its role in prostate cancer progression is currently lacking." (PMID 36674564, 2023). "ANO7 is only expressed in prostate cells, has an unknown function, and is negatively correlated with the prognosis of prostate cancer." (PMID 36836529, 2023). "A similar function has been suggested for ANO7 in the context of prostate cancer that might also apply for other Anoctamin family members." (PMID 35207106, 2022). "The same observations apply to ANO7, a potential scramblase that is upregulated in prostate cancer." (PMID 35207044, 2022). "This study aimed to analyze ANO7 expression and its clinical significance in prostate cancer (PCa)." (PMID 33628598, 2021). "ANO7, a gene hyper-methylated in prostate cancer identified by our study, has been reported that it may act as a target gene for antibody-based immunotherapy." (PMID 27556923, 2016). "Since cancer cells have been found to synthesize de novo fatty acids in excess, and prostate cancer becomes aggressive with overexpression of fatty acid synthase, suppressing the levels of de novo fatty acids by elevated ANO7 may offer a mechanism to limit cancerous lipogenesis." (PMID 39923095, 2025). "ANO7 is a prostate-specific gene, and consistent with the protective ANO7 missense variant reported here, an ANO7 eQTL (2:241195850:G:A) common in the European population (MAF = 2.10%) has previously been found to be associated with both prostate cancer risk and severity." (PMID 39971927, 2025). "Understanding the mechanisms by which ANO7 affects mitochondrial function and limits the de novo fatty acid levels may lead to the development of targeted therapies and the identification of potential biomarkers for aggressive prostate cancer cases." (PMID 39923095, 2025). "ANO7 exhibits restricted tissue expression and is highly expressed in normal and cancerous prostate where it localizes to apical and lateral membrane regions and may regulate cell aggregation; accordingly ANO7 represents a target for prostate cancer immunotherapy." (PMID 19997627, 2009). "ANO7, also known as NGEP (for New Gene Expressed in Prostate) is an androgen-dependent gene known to be specifically expressed in epithelial cells of prostate cancer and in normal prostate, but not in other tissues." (PMID 23826159, 2013).
breast carcinoma (3 papers, 2015 to 2024). "Furthermore, a growing body of evidence has recently demonstrated the pathogenic role of ANO7 in several other cancers, including breast cancer, thyroid cancer, and neuroblastoma." (PMID 38224713, 2023). "We also identified some category 2 genes such as ARL6IP5, RAET1E, and ANO7 that could be crucial for breast cancer development and prognosis." (PMID 25803781, 2015). "We also identified some genes such as ARL6IP5, RAET1E, and ANO7 that could be crucial for breast cancer development and prognosis." (PMID 25803781, 2015).
colon cancer (3 papers, 2020 to 2023). "Further analysis using Pathway Studio elucidated a molecular and functional network of ANO7-correlated genes related to proteolysis and mucin dynamics in colon cancer." (PMID 38224713, 2023). "We discovered new colon cancer related genes including AC007952.4, NEK8, CHRM3, ANO7, B3GNT6, NEURL1, ODC1 and KCNMA1." (PMID 36944972, 2023).
adenoma (2 papers, 2023 to 2024). A neoplasm arising from the epithelium. "We collected the resected carcinoma tissues from CRC patients and conducted immunohistochemical (IHC) staining analysis to examine the expression of some representative genes including NEK8, CHRM3, ANO7, B3GNT6, NEURL1, ODC1 and KCNMA1 in colon normal tissue, adenoma tissue and carcinoma tissues." (PMID 36944972, 2023).
autosomal dominant polycystic kidney disease (1 paper, 2023). Autosomal dominant form of polycystic kidney disease. "At the same time, it also contributes to the progression of autosomal dominant polycystic kidney disease (ADPKD), while ANO7 upregulation is linked to prostate cancer." (PMID 35648332, 2023).
colorectal cancer (1 paper, 2024). A primary or metastatic malignant neoplasm that affects the colon or rectum. "In conclusion, we suggest that ANO7 and SLC38A4 serve as prognostic biomarkers in colorectal cancer." (PMID 39114022, 2024).
lymph node metastasis (1 paper, 2021). "Low ANO7 expression was linked to advanced tumor stage (P < 0.0001), high classical and quantitative Gleason grade (P < 0.0001 each), presence of lymph node metastasis (P < 0.0001), high preoperative PSA level (P < 0.0001), and positive surgical margin (P < 0.0001)." (PMID 33628598, 2021).
metastatic cancer (1 paper, 2023). A carcinoma which has spread from the original site of growth to another anatomic site. "The strong association of ANO7 and PrCa makes the gene very interesting in the context of cancer progression, whereas the reduced expression in advanced and metastatic cancer may indicate that the gene has lost its relevance in cellular functions in advanced cancer." (PMID 36674564, 2023).
mucinous adenocarcinoma (1 paper, 2023). An invasive adenocarcinoma composed of malignant glandular cells which contain intracytoplasmic mucin. "Furthermore, COAD patients diagnosed with mucinous adenocarcinoma exhibited significantly higher ANO7 expression levels compared to those with adenocarcinoma." (PMID 38224713, 2023).
cancer (12 papers, 2018 to 2025). A tumor composed of atypical neoplastic, often pleomorphic cells that invade other tissues. "Of the 17 ANO7 variants represented within our 473 genotyped southern African PCa cases and 307 cancer-free controls, six identified PDVs were overlapped with our sequencing data." (PMID 37749167, 2024). "Our data suggest that loss of ANO7 expression is ERG dependent as ANO7 protein levels were clearly lower in ERG-positive than in ERG-negative cancers." (PMID 33628598, 2021). "The striking prognostic role of ANO7 loss is also demonstrated by its prognostic relevance in multiple subgroups of cancers with identical traditional (3+4, 4+3, ≥ 8; P < 0.0005 each) and quantitative Gleason grade (3 of 7 groups)." (PMID 33628598, 2021). "A striking prognostic impact of ANO7 loss was also seen in the subset of 982 PTEN-deleted cancers (P = 0.0033)." (PMID 33628598, 2021). "The insights into the functional role of ANO7 in the prostate, as elucidated in this study, offers promising opportunities for further research in the field of prostate function and cancer." (PMID 39923095, 2025). "•Evaluation of survival analysis, methylation, and mutation patterns of ANO7 and SLC38A4 across various cancers." (PMID 39114022, 2024). "The reduction in the fraction of nuclear transcripts in high-grade cancer suggests that along with the downregulation of ANO7 gene expression, nuclear retention is also attenuated." (PMID 36674564, 2023). "The mean nuclear proportion of ANO7 transcripts was 88.8% in benign and low-grade cancer and 77.7% in high-grade cancer, and the difference was statistically significant (p = 0.0193)." (PMID 36674564, 2023). "In the RNA-FISH images, the signal for ANO7 mRNA in benign glands and low-grade cancer appeared as small point-formed foci and dense clusters of a few individual foci; the latter always colocalized with the nuclear staining." (PMID 36674564, 2023). "Due to the similarity of ANO7 expression in benign glands and low-grade cancer, these samples were combined and compared against high-grade cancer." (PMID 36674564, 2023). "Studies have shown that ANO7 mRNA expression decreases from low-grade to high-grade cancer and that ANO7 is downregulated in metastatic PrCa." (PMID 36674564, 2023). "The particularly low levels of ANO7 expression in PTEN-deleted cancers are consistent with a direct or indirect functional interaction between ANO7 and the PTEN/AKT pathway." (PMID 33628598, 2021). "The prognostic impact of reduced PSA was very strong, comparable to the role of ANO7 loss, and also found in PTEN-deleted cancers." (PMID 33628598, 2021). "A particularly strong association was found between reduced ANO7 staining and the presence of PTEN (10q23) deletions, which was highly significant in all cancers as well as in ERG-negative and ERG-positive cancers (P < 0.0001 each)." (PMID 33628598, 2021). "ANO7 was strongly expressed in normal prostate glandular cells but often less abundant in cancer cells." (PMID 33628598, 2021). "Strong ANO7 staining was less prevalent in cancers harboring TMPRSS2:ERG rearrangements (24%) and ERG expression (25%) than in cancer lacking ERG fusions (43%) or ERG expression (45%, P < 0.0001 each)." (PMID 33628598, 2021). "ANO7 staining was interpretable in 13,594 cancer tissues and considered strong in 34.4%, moderate in 48.7%, weak in 9.3%, and negative in 7.6%." (PMID 33628598, 2021). "Novel to this study, we identify ANO7 as a potential oncogenic driver in African men, through the formation of gene fusions with the cancer-related genes G3BP1 and PPFIA4, involved in androgen receptor (AR) and mitogen-activated protein kinase (MAPK) signalling, respectively." (PMID 37749167, 2024). "As a result, ANO7 holds promise as an intriguing target for cancer biomarkers." (PMID 38224713, 2023). "Furthermore, we show that ANO7 mRNA is enriched in the nuclei of the luminal cells at 89% in benign ducts and low-grade cancer, and at 78% in high-grade cancer." (PMID 36674564, 2023).
cancer (continued). "Therefore, future studies aiming at elucidating the role of ANO7 should focus on benign tissue and low-grade cancer." (PMID 36674564, 2023). "In high-grade cancer, in which ANO7 is expressed at a very low level, the transcript distribution might be affected by possible off-target signals; we did indeed observe a greater variation in signal localization in high-grade cancer compared to low-grade cancer." (PMID 36674564, 2023). "Therefore, it could be concluded that ANO7 mRNA is retained in the nucleus both in benign tissue and in cancer." (PMID 36674564, 2023). "We entered the ANO7 and SLC38A4 gene as input and extracted the results of sample samples, cancer stages, gender and histological subtypes in CRC." (PMID 39114022, 2024). "We conducted an analysis of ANO7 and SLC38A4 expression in cancer and normal tissues using data from TCGA and GTEx datasets." (PMID 39114022, 2024). "Anoctamin 7 (ANO7), also called TMEM16G, codes for a member of the anoctamin family which has been reported to be correlated with cancer progression." (PMID 37749167, 2024). "All these analyses identified ANO7 as a strong independent prognostic feature in the entire cohort and also in the subgroups of ERG-negative and -positive cancers (P < 0.0001 each)." (PMID 33628598, 2021). "Apart from ANO1, other members of the anoctamin family were also correlated with cell proliferation and cancer development, like ANO5 (TMEM16E), ANO7 (TMEM16G) and ANO9 (TMEM16J)." (PMID 30893776, 2019). "Nonetheless, ANO7 nuclear enrichment was consistently high in all analyzed ROIs in high-grade cancer, whereas the negative control dabB showed high variability." (PMID 36674564, 2023). "In low-grade cancer, the ANO7 signal pattern was very similar to that observed in benign glands and no ANO7 mRNA was detected in the basal cells (red arrowheads)." (PMID 36674564, 2023). "In contrast to ANO7, PPIB expression gradually increased from benign to high-grade cancer." (PMID 36674564, 2023). "That the interaction with PTEN is not responsible for the prognostic impact of reduced ANO7 expression is demonstrated by its retained prognostic role in PTEN-deleted cancers." (PMID 33628598, 2021). "While ANO5, ANO7, and ANO9 may also be relevant for growth of cancers, evidence has been provided for a role of ANO6 (TMEM16F) in regulated cell death." (PMID 30893776, 2019). "In analogy to the PSA situation, we consider it possible that ANO7 is another important component of prostate epithelial cells without a cancer-specific role and that a reduced expression might indicate cellular dedifferentiation." (PMID 33628598, 2021).
tumor (4 papers, 2021 to 2024). "Because the risk SNP rs77559646 is now shown to cause loss of ANO7 protein, we propose that loss of ANO7 may actually contribute to tumor progression, i.e. that ANO7 acts as a tumor suppressor." (PMID 35043958, 2022). "Lost or reduced ANO7 staining showed significant associations with adverse tumor features." (PMID 33628598, 2021). "These contradictory findings prompted us to evaluate the potential prognostic impact of ANO7 expression in PCa by using our tissue microarray (TMA) comprising tumor samples from more than 17,000 individual patients." (PMID 33628598, 2021). "We consider it thus unlikely that ANO7 exerts a potential tumor suppressive function through impacting tumor cell proliferation." (PMID 33628598, 2021). "These impairment on ANO7 protein may be relevant to the observed overexpression in malignant tumour cells." (PMID 37749167, 2024). "Here we interrogate ANO7 germline and tumour genome sequencing (n = 166), as well as array-based genotype data (n = 780), providing the first insights for the relevance of ANO7 and aggressive PCa presentation within the genetically diverse southern African population identifier." (PMID 37749167, 2024). "The fact that none of the homozygous rs77559646 carriers had been diagnosed at a particularly young age supports their view that loss of ANO7 does not drive tumor initiation." (PMID 35043958, 2022). "We propose that ANO7 acts as a tumor suppressor in the prostate." (PMID 35043958, 2022). "This indicates that ANO7 could be a surrogate of molecular driver of tumor aggression in PCa that is yet to be discovered." (PMID 33628598, 2021). "Tumor progression data thus clearly includes downregulation of ANO7 expression, but does not reveal whether loss of ANO7 is a cause or a consequence of tumor progression." (PMID 35043958, 2022). "In our patients, tumor cell proliferation was only marginally linked to ANO7 expression and significant associations could often not be found in homogeneous subgroups." (PMID 33628598, 2021). "Scenario 3 included ANO7 expression, preoperative PSA, clinical tumor stage (cT stage), and Gleason grade obtained on the prostatectomy specimen." (PMID 33628598, 2021).
adenocarcinoma (2 papers, 2023). A common cancer characterized by the presence of malignant glandular cells. "In high-grade adenocarcinoma, ANO7 protein was downregulated or lost." (PMID 36674564, 2023).
ANO7 also shares sentences with these, for which no sentence is quoted: aggressive (1 paper); bladder cancer (1); colon adenocarcinoma (1); head and neck squamous cell carcinoma (1); neuroblastoma (1); rectum adenocarcinoma (1); thyroid cancer (1).